MYL9 (myosin light chain 9)
Diseases named in the same sentence as MYL9 in open-access papers (continued):
Sharing a sentence is not in itself a finding about the gene and the disease.
tumor (continued). "MYL9 protein expression increases significantly with tumor recurrence." (PMID 34974798, 2022). "MYL9 played an important role not only in oncogenesis but also could be used as a sensitive biomarker for tumor diagnosis." (PMID 34729929, 2022). "In the GO data set, we found that “muscle contraction,” “myosin filament,” “focal adhesion,” and “calmodulin binding” might be involved in the effect of MYL9 on tumor pathogenesis." (PMID 34729929, 2022). "MYL9 expressed lower in tumor tissues than normal tissues at mRNA and protein level." (PMID 35768705, 2022). "Therefore, the value of MYL9 for diverse tumor diagnosis and therapy was different, which deserved further investigation." (PMID 34729929, 2022). "CSRP1 and MYL9 will decrease when tumor progressed from T2 to T4 (P = 0.032 and P = 0.047)." (PMID 35768705, 2022). "Myl9 plays a critical role in immune infiltration, tumor invasion, and metastasis." (PMID 35743193, 2022). "MYL9 (myosin light chain 9) has been reported to play an important role in tumor progression in PC." (PMID 31396486, 2019). "There were also alterations in Myl9 levels which is mainly a protein, enhancing tumor progression." (PMID 31391093, 2019). "Patients with high MYL9 expression in tumor cells have poor OS and recurrence-free survival." (PMID 28388691, 2017). "Our study suggests that MYL9 expression in tumor cells might be a promising prognostic biomarker and a potentially viable therapeutic target in ESCC." (PMID 28388691, 2017). "We speculate that MYL9 is a possible therapeutic target for preventing invasion in patients with ESCC with high MYL9 levels in the primary tumor cells." (PMID 28388691, 2017). "MYL9 expression was often higher in tumor cells at the edge of the tumor tissue." (PMID 28388691, 2017). "Indeed, there is a significant increase in RhoC, Cdc42 and MYL9 expression levels in metastasis versus primary tumours, indicating that drivers of actomyosin contractility are selected during HCC metastatic dissemination." (PMID 27941881, 2017). "In the present study, MYL9 expression levels were often higher in tumor cells at the invasion edge of the ESCC tissues, suggesting that MYL9 may play a role in ESCC invasion." (PMID 28388691, 2017). "Notably, YAP-1 signalling preserved expression of both integrin beta-1 and ITGA11 implying auto-regulation similarly to YAP-1’s function in cancer-associated fibroblasts, where MYL9 was a key regulator of the ECM and tumour invasion." (PMID 27535340, 2016). "Therefore, we believe that MYL9 may affect the tumor immune microenvironment by regulating the secretion of CCL2 and TGF-β1 from CAFs, and is closely related to M2 macrophage infiltration." (PMID 37926835, 2023). "Therefore, MYL9 expression is closely related to the prognosis of various tumors and tumor immunity, and may be a potential target for tumor prognosis and immunotherapy." (PMID 37926835, 2023). "In addition, whether CCL2 and TGF-β1 can promote tumor progression in addition to affecting the tumor immune microenvironment and the regulatory mechanism of MYL9 require further investigation." (PMID 37926835, 2023). "Interestingly, the IHC results showed that MYL9 was mainly expressed in the tumor stroma." (PMID 37926835, 2023). "Our first pan‐cancer analyses of MYL9 indicated statistical correlations of MYL9 expression with clinical prognosis, immune cell infiltration across multiple tumors, which aids in understanding the role of MYL9 in tumorigenesis from the perspective of clinical tumor samples." (PMID 34729929, 2022). "We speculated that MYL9 and CNN1 may act as tumor suppressor genes in human bodies, however, with the development and progression of CRC, the two hub genes may be captured by tumor cells and turned to be harmful genes, therefore protecting tumor cells becomes the major role of MYL9 and CNN1." (PMID 32127961, 2020). "Therefore, we focused on aberrant MYL9 expression in tumor cells to investigate its clinical value." (PMID 28388691, 2017).
tumor (continued). "The CRYAB, MYL9, and SORBS1 genes also act as tumor suppressors through involvement in different signaling pathways." (PMID 41439026, 2025). "We identified MMP11 and MYL9 as potential biomarkers for advanced disease stages and underscore the context-dependent role of DEFA family genes in tumor progression—supported by stage-specific pathway analyses and cross-species validation." (PMID 41009818, 2025). "Myosin light chain 9 (MYL9) and myosin heavy chain (MYH11) play a vital role in immune infiltration, tumor invasion, and metastasis and, therefore, serve as potential targets for cancer treatment." (PMID 38626166, 2024). "MYL9 is critically involved in ECM remodeling and stiffness, and induced invasion of tumor cells through binding to actin filaments to control cytoskeletal dynamics." (PMID 37031206, 2023). "MYL9 is predominantly expressed in the CAFs of CRC tissues and can indirectly influence tumor biology and EMT by affecting CAFs protein expression." (PMID 37926835, 2023). "After intersecting genes in the yellow module of WGCNA with DEGs, we identified five myCAFs marker genes defined by previous single-cell sequencing that were significantly down-regulated in tumor tissues, including ACTA2, MYL9, TAGLN, TPM1, and TPM2." (PMID 35309916, 2022). "In the current study, strong interaction was predicted between TPM2 and myosin light chain 9 (MYL9), which deserves to be further investigated to unveil its potential impact on the tumor recurrence of CRC." (PMID 33897765, 2021). "In their study, tumor myofibroblasts were identified based on the expression of α-SMA, melanoma cell adhesion molecule (MCAM), myosin light chain kinase (MYLK), and myosin light chain 9 (MYL9)." (PMID 31106200, 2019). "Among these were several genes with known tumour suppressor activity (e.g. FLNA, FBLN1, MYL9, CLIC4 and SEC23A)." (PMID 27124473, 2016). "Although we demonstrated that DEFA3 inhibits proliferation and migration of CT26 cells in vitro, and linked MMP11/MYL9 expression to advanced CRC in human datasets, we did not test the functional impact of these genes in living tumor models." (PMID 41009818, 2025). "MYL9 expression is high in several non-metastatic cancer cell lines and displays differential expression depending on the tumor type and the progression of cancer." (PMID 39768172, 2024). "In this study, we demonstrated that MYL9 expression in CRC occurs mainly in CAFs but not in tumor cells." (PMID 37926835, 2023). "According to our results, MYL9 expression in CRC tissues was significantly higher in CAFs than in tumor cells, and its upstream and downstream regulatory mechanisms in CAFs are different from those in tumor cells." (PMID 37926835, 2023). "In addition, tissue immunofluorescence showed that MYL9 and the CAFs marker protein a-SMA were co-expressed in the tumor stroma." (PMID 37926835, 2023). "The relationship between MYL9 expression and CRC clinical staging and immunotherapy is closer in CAFs than in tumor cells; therefore, studies using CAFs as a model deserve more attention when exploring tumor molecular targets in clinical research." (PMID 37926835, 2023). "Tissue immunofluorescence showed that MYL9 was stably expressed in CAFs rather than in tumor cells, considering that the primary CAFs that we isolated were also stably cultured and passaged." (PMID 37926835, 2023). "The expression of CSRP1, MYL9 and SNAI2 changed in different tumor stage." (PMID 35768705, 2022). "Recent studies have shown that myosin light chain 9 (MYL9) plays a vital role in immune infiltration, tumor invasion, and metastasis; however, the prognostic and immunological role of MYL9 has not been reported." (PMID 34729929, 2022). "Univariate analysis of clinicopathological data indicated that patient or tumor factors did not affect MYL9 expression." (PMID 34821071, 2022). "In fact, MYL9 phosphorylation levels in primary tumor tissues, including in ESCC, have not been addressed." (PMID 28388691, 2017).
tumor (continued). "In conclusion, MYL9 expression is significantly upregulated in ESCC tumor cells compared to adjacent non-tumor epithelial cells, especially in poorly differentiated tumors." (PMID 28388691, 2017). "Here, we examined MYL9 expression based on its presence in the tumor cell cytoplasm without consideration of stromal portion expression." (PMID 28388691, 2017). "MYL9 expression in the tumor samples was higher than that in the paired ANT, but not very obviously so in some paired samples." (PMID 28388691, 2017). "The enhanced secretion of lysophosphatidic acid (LPA) and TGF-β, supposedly by tumor cells, initially promotes matrix remodeling by stromal fibroblast, a process that requires Rho/ROCK/ Myosin Light Chain 9 (MYL9)/MLC-mediated changes in their contractile actin cytoskeleton." (PMID 27854331, 2016). "More precisely, FLNA FBLN1, MYL9, CLIC4 all have demonstrated tumour suppressor activity." (PMID 27124473, 2016). "Moreover, the expression levels of MYL9 and TPM2, but not MSN were significantly associated with the advanced TNM stage, implying that MYL9 and TPM2 may play a key role in tumor progression, and predicted a worse outcome in CRC." (PMID 37031206, 2023). "Therefore, we found that MYL9 was mainly localized to CAFs rather than to tumor epithelial cells and that its protein expression was elevated in CRC." (PMID 37926835, 2023). "Therefore, we intended to verify the expression of MYL9 in CAFs, tumor cell lines (LoVo, SW480, and HCT116), and normal cell lines (NCM460) by western blotting and found that MYL9 was stably expressed in CAFs and was less expressed in CRC and normal cell lines." (PMID 37926835, 2023). "We therefore hypothesized that the phosphorylation of MYL9 or CNN1 is the key of cell migration process on solid substrates in tumor microenvironment but not in the normal stroma microenvironment, leading to the aggressive progression of CRC." (PMID 32127961, 2020). "However, initial analysis of 17 paired ESCC samples from NCBI/GEO/GES20347 showed that MYL9 mRNA expression was not significantly different between the ESCC tumor tissues and the matched ANT (p = 0.5310)." (PMID 28388691, 2017). "Nevertheless, the effect of MYL9 on tumor cell differentiation has not been investigated." (PMID 28388691, 2017). "Furthermore, six tumor progression genes (GNAI2, ODC1, APP, TNFRSF12A, BASP1, and LARP6) and nine migration and metastasis‐related genes (MSN, FLOT1, LAMB3, MYL9, ITGB1, FTH1, TPM4, and PMEPA1), which could explain the invasive characteristics of SCC, were identified." (PMID 40776410, 2025). "Except for MYL9 and MYLK that were oppositely regulated in PHKs versus immortalized keratinocytes and HPV+ tumor cells, none of these genes was DE in normal keratinocytes after CDV exposure." (PMID 23702334, 2013). "To examine whether MYL9 is also highly expressed in human ESCC clinical samples, we performed western blotting on eight ESCC tumor samples that were matched with adjacent noncancerous tissue samples (ANT)." (PMID 28388691, 2017).
cancer (36 papers, 2010 to 2025). A tumor composed of atypical neoplastic, often pleomorphic cells that invade other tissues. "YAP1, a direct binding partner of MYL9 linked to a pro-cancer signaling pathway, is transcriptionally activated when a cell senses a stiff ECM." (PMID 39768172, 2024). "One potential mechanism involves the transcription factors associated with the EMT process, such as ZEB1, which can directly bind to the MYL9 promoter in cancer-associated fibroblasts (CAFs)." (PMID 39768172, 2024). "The expressions of MYL9 were significantly associated with the infiltration of cancer‐associated fibroblasts, B cell, CD8+T cell, CD4+T cell, macrophage, neutrophil, dendritic cell in different tumors as well as immune markers." (PMID 34729929, 2022). "Our results indicated that MYL9 can serve as a prognostic signature in pan‐cancer and is associated with immune infiltration." (PMID 34729929, 2022). "We further demonstrated that MYL9 deficiency inhibited cancer cell migration using scratch and transwell assays." (PMID 36589754, 2022). "Studies have also found that YAP remodels the extracellular matrix and promotes cancer cell migration by regulating MYL9 and the actomyosin cytoskeleton in cancer-associated fibroblasts." (PMID 36589754, 2022). "Few studies have examined the association between MYL9 expression and cancer." (PMID 34821071, 2022). "The expression of MYL9 was significantly associated with prognosis in several cancers." (PMID 35743193, 2022). "Subsequently, we integrated information on MYL9 binding components and genes associated with MYL9 expression in all tumors and performed a series of enrichment analyses to identify the potential role of muscle contraction and local adhesion in cancer etiology or pathogenesis." (PMID 34729929, 2022). "MYL9 can serve as a prognostic signature in pan‐cancer and is associated with immune infiltrating." (PMID 34729929, 2022). "MYL9 can serve as a prognostic signature in pan‐cancer and is associated with immune infiltration." (PMID 34729929, 2022). "Notably, we noticed that MYL9 plays a critical role in enhancing matrix stiff and invasion of cancer-associated fibroblasts (CAFs), and as the matrix becomes stiffer, isometric tension within the cell increases, leading to Src activation and the subsequent activation of YAP." (PMID 37031206, 2023). "The upregulated genes were associated with extracellular matrix remodeling and cancer pathways, including LAMC1-3, COL9A2, COL1A1, MYL9, MYH11, and KAT2A." (PMID 39735192, 2024). "For cancer cells to exist in a solid tumor mass, MYL9 will increase the epithelial characteristics, such as increased E-cadherin and decreased N-cadherin levels, decreased invasive capabilities, and increased cell–cell contacts." (PMID 39768172, 2024). "MYL9, also known as MLC2 and MRLC1, is a protein-encoding gene that has been considered to play an important role in various cancers in recent years." (PMID 37926835, 2023). "Although some bioinformatic studies have found that MYL9 plays a role in cancer migration ability and metastasis, molecular proof is scarce about MYL9 function in GC cells." (PMID 36589754, 2022). "This pan‐cancer study is the first to show a relatively comprehensive understanding of the prognostic and immunological roles of MYL9 across different cancers." (PMID 34729929, 2022). "To investigate the role of MYL9 in regulating the ability of cancer cells in patients to become malignant, we classified patients with PDAC into three groups, based on MYL9 staining intensities." (PMID 34821071, 2022). "The purpose of this study was to explore the potential prognostic and immunological roles of MYL9 in human cancers by public datasets mainly including the cancer genome atlas (TCGA) and Gene expression omnibus." (PMID 34729929, 2022). "Upregulation of MYL9 has been observed in several cancers, including colorectal cancer and glioblastoma, where it is thought to promote the proliferation and migration of the cancer cells." (PMID 35802750, 2022).
cancer (continued). "To elucidate the involvement of MYL9 in cancer progression, we performed in vitro assays by manipulating MYL9 gene expression." (PMID 34821071, 2022). "Additional studies regarding the effect of MYL9 expression on the invasive ability of cancer cells in PDAC are necessary." (PMID 34821071, 2022). "Results showed that the level of MYL9 expression and the degree of CAFs infiltration affected the CS of cancer patients, and they played different or adverse roles in different tumors." (PMID 34729929, 2022). "Extracellular matrix remodeling and cancer cell invasion require actomyosin cytoskeleton, and MYL9 is regulated by YAP and participates in matrix stiffening." (PMID 36589754, 2022). "The expression pattern and prognostic value of MYL9 were analyzed across multiple public datasets in different cancer." (PMID 34729929, 2022). "These although preliminary results seem to point out an important role of MYL9 in cancer development and further investigation should be promising for the better understanding of cancer pathophysiology." (PMID 36273228, 2022). "An increasing number of researches have validated that MYL9 can play a role in the proliferation, metastasis and invasion of cancer cells." (PMID 34974798, 2022). "Several triple-evidenced genes (MMP9, MMP11, CXCL12, MYL9) appear in three out of the five significantly enriched pathways and in more than half of the 13 cancers." (PMID 30729033, 2019). "We also explored the MYL9 expression patterns in cervical (n = 20), ovarian (n = 20), colorectal (n = 40), and hepatocellular (n = 10) carcinoma samples." (PMID 28388691, 2017). "The MYL9 axis can regulate both protein activity and cellular function by modifying signaling pathways and post-translational modifications (PTMs) that have deleterious downstream effects on certain cancer types." (PMID 39768172, 2024). "Considering that whether MYL9 is an important immunotherapy target in tumors requires further study, we performed a pan-cancer analysis of MYL9 expression and immunomodulators." (PMID 37926835, 2023). "For immune-related genes, the expression of genes involved in the categories of tight junction such as MYH11, PPP2R2C, and MYL9, cancer development such as TAGLN and CALD1, and acquired immunity such as PCP4 and CXCL13 was upregulated in the LP group when compared with that in the CON group." (PMID 37731924, 2023). "Therefore, our pan‐cancer analysis showed that MYL9 is a potential prognostic factor that contributed to the clinical treatment and prevention of tumors." (PMID 34729929, 2022). "As cell contractility and motility increase during metastasis, whether MYL9 affects cancer metastasis directly via cellular motility enhancement and EMT status changes remains unclear." (PMID 36589754, 2022). "What MYL9 is doing in cancer cells remains unclear, but it thought to promote proliferation and cell migration." (PMID 35802750, 2022). "Therefore, we attempted to explore the underlying mechanisms by using the Kaplan–Meier plotter database and to assess the relationship between the expression of MYL9 and the clinicopathological factors of cancer patients." (PMID 34729929, 2022). "The combined information of the two databases manifested that the effects of MYL9 gene on oncogenesis and progression mainly involved muscle contraction and focal adhesion, which will provide a direction for clinical diagnosis and treatment of cancer patients." (PMID 34729929, 2022). "In conclusion, our first pan‐cancer analysis of MYL9 demonstrated statistical correlations of MYL9 expression with clinical prognosis, immune infiltrating across multiple cancers, which aids in understanding the role of MYL9 in tumorigenesis from the perspective of clinical cancer samples." (PMID 34729929, 2022). "Previous studies have demonstrated that the functional role of MYL9 may differ, depending on the cancer type." (PMID 34821071, 2022).